MIR5690 (microRNA 5690)
Synonyms: hsa-mir-5690
Gene: MicroRNA gene on chromosome 6 (35,664,717 to 35,664,789, reverse strand). Ensembl gene ENSG00000265527.
Homologues: Orthologues: chimpanzee MIR5690 (100% identical).
Diseases named in the same sentence as MIR5690 in open-access papers:
MIR5690 is named in the same sentence as 1 disease in open-access papers, as found by Europe PMC text mining. Sharing a sentence is not in itself a finding about the gene and the disease. The quoted sentences say what the papers report.
chordoma (1 paper, 2025). Chordomas are rare malignant tumors arising from embryonic remnants of the notochord in axial skeleton. "The heatmap revealed that MIR5690, SNORD15B, RAB3B were highly expressed in chordoma, along with the generally reported chordoma regulators, such as KRT19, LYST, and EGFR." (PMID 40135815, 2025).